PRL (prolactin)
Description:
Prolactin acts primarily on the mammary gland by promoting lactation.
Synonyms: pPRL; GHA1
Tractability: Small molecule: it has a binding pocket of medium quality. Antibody: its Gene Ontology location is reachable by antibodies, with high confidence; UniProt places it where antibodies can reach, with medium confidence; UniProt predicts a signal peptide or a membrane-spanning region.
Safety:
Unwanted effects reported when the protein is acted on. In parentheses: how it was acted on, where the effect was seen, and who reports it.
Increased, Adenomas/carcinomas (mammary) (activation; source: AOP-Wiki)
Gene: Protein-coding gene on chromosome 6 (22,287,244 to 22,302,826, reverse strand). Ensembl gene ENSG00000172179.
Subcellular location: Secreted
Pathways (Reactome):
Immune System: Growth hormone receptor signaling; Prolactin receptor signaling
Developmental Biology: Developmental Lineage of Mammary Gland Alveolar Cells
Metabolism of proteins: Amyloid fiber formation
Gene Ontology:
Molecular function: protein binding; hormone activity; prolactin receptor binding
Biological process: negative regulation of endothelial cell proliferation; positive regulation of canonical NF-kappaB signal transduction; positive regulation of miRNA transcription; positive regulation of receptor signaling pathway via JAK-STAT; prolactin signaling pathway; cell surface receptor signaling pathway; female pregnancy; mammary gland development; negative regulation of angiogenesis; positive regulation of lactation; response to nutrient levels
Cellular component: endosome lumen; extracellular region
Genetic constraint (gnomAD): Loss-of-function variants: 25 observed, 24.26 expected, observed/expected ratio (o/e) 1.03, 90% interval 0.75 to 1.44. The upper end of that interval is the gene's LOEUF score, 1.44, which puts it in group 5 of 6, group 1 being the genes least tolerant of losing a copy. Missense variants: 243 observed, 296.71 expected, observed/expected ratio (o/e) 0.82, 90% interval 0.74 to 0.91. Synonymous variants: 118 observed, 120.07 expected, observed/expected ratio (o/e) 0.98, 90% interval 0.85 to 1.14.
Homologues: Orthologues: chimpanzee PRL (99% identical), macaque PRL (98% identical), pig PRL (80% identical), dog PRL (80% identical), rabbit PRL (79% identical), tropical clawed frog prl (61% identical), mouse Prl (61% identical), rat Prl (61% identical), guinea pig Prl (55% identical), mouse Prl2a1 (43% identical), guinea pig Prlrp2 (42% identical), rat Prl7b1 (42% identical), and 49 more. Paralogues in human: CSH1 (23% identical), CSH2 (23% identical), GH1 (23% identical), CSHL1 (22% identical), GH2 (22% identical).
Diseases named in the same sentence as PRL in open-access papers:
PRL is named in the same sentence as 704 diseases in open-access papers, as found by Europe PMC text mining. Sharing a sentence is not in itself a finding about the gene and the disease. The quoted sentences say what the papers report.
hyperprolactinemia (681 papers, 1992 to 2026). Abnormally high level of prolactin in the blood. "Marked hyperprolactinemia in the setting of a hemorrhagic sellar mass can create diagnostic uncertainty between stalk effect and a prolactin-secreting tumor, with important implications for initial management." (PMID 41939625, 2026). "For instance, macroprolactinemia, caused by antiprolactin antibodies (mostly IgG) bound to prolactin, can lead to biologically inactive hyperprolactinemia detected by the assay." (PMID 41017446, 2026). "Recent clinical observations describe strong associations between elevated serum PRL states including postpartum and lactational periods, prolactinomas, and antipsychotic‐induced hyperprolactinemia and the onset or recurrence of IGM." (PMID 41476991, 2025). "It is well established that hyperprolactinemia causes infertility, and thus, the elevated prolactin present in lactation seems a likely candidate to be involved in suppressing fertility during lactation." (PMID 39819370, 2025). "Patients with GLM demonstrate significantly elevated PRL levels compared to healthy controls, with lactation-associated hyperprolactinemia identified as a primary risk factor through its promotion of ductal secretion abnormalities." (PMID 40948778, 2025). "Clinical studies report an association between migraine and hyperprolactinemia,19 which fits with preclinical evidence of a mechanistic link between prolactin signaling and trigeminal nociception." (PMID 41052788, 2025). "It is recommended to investigate elevated prolactin levels in PCOS patients to identify the underlying causes of hyperprolactinemia, particularly macroprolactinemia." (PMID 40656428, 2025). "There exists a complex relationship between hyperprolactinemia and metabolic syndrome in prolactinoma patients, with the normalization of PRL levels associated with a reduction in BMI." (PMID 39904877, 2025). "Despite hyperprolactinaemia being a well-recognised cause of infertility, the specific role that prolactin plays in lactational infertility, as distinct from other suckling- or metabolic-related cues, is currently unclear." (PMID 39819370, 2025). "A similar model has been observed with prolactin: its levels can be increased by any type of stress, whereas hyperprolactinemia in patients with prolactinomas has been linked with several psychological symptoms, such as anxiety and depression." (PMID 41210497, 2025). "A major indication for dopamine agonists, including bromocriptine and cabergoline, is hyperprolactinemia usually caused by a prolactin-secreting pituitary adenoma." (PMID 40168298, 2025). "Hyperprolactinemia is a syndrome of hypothalamic-pituitary axis reproductive endocrine disorders, expressed by elevated serum prolactin levels and its associated clinical manifestations." (PMID 41333774, 2025). "All athletes in the study presented with plasma prolactin concentrations within the normal reference range ruling out hyperprolactinemia as a cause of MD." (PMID 39816167, 2025). "Hyperprolactinemia is associated with headache, and improvement following prolactin‐lowering therapy has been reported in observational studies." (PMID 41052788, 2025). "Laboratory tests showed mildly elevated prolactin levels of 36 ng/mL (reference < 25 ng/mL), consistent with psychotropic-associated hyperprolactinemia." (PMID 41561265, 2025). "The patient demonstrated only mild prolactin elevation (36 ng/mL), a range commonly reported in drug-induced hyperprolactinemia and sufficient to produce galactorrhea in susceptible individuals." (PMID 41561265, 2025). "Hyperprolactinemia is associated with migraine‐like headache, and preclinical studies show that prolactin enhances trigeminal excitability, particularly in females." (PMID 41052788, 2025). "Antipsychotics are the most relevant of all medications causing hyperprolactinemia, as they increase prolactin levels more frequently and at greater intensity than other drugs." (PMID 38578473, 2024).
hyperprolactinemia (continued). "While risperidone, an antipsychotic that can be used for ASD management, is commonly known to induce hyperprolactinemia, the association between amitriptyline and elevated prolactin is less frequently described in the literature." (PMID 38826982, 2024). "The association between hyperprolactinemia and metabolic syndrome suggests that PRL itself acts as a regulator of body weight, with improvement in both BMI and metabolic profile credited to DAs therapy." (PMID 38510701, 2024). "Numerous studies have associated elevated levels of prolactin in maternal serum (hyperprolactinemia), amniotic fluid, or cervicovaginal secretions with pregnancy loss and/or preterm birth." (PMID 39763651, 2024). "The clinical signs and symptoms of PRL are mainly related to hyperprolactinemia, which is the hallmark of these tumors." (PMID 38645431, 2024). "Improvements in bone density in men with both hyperprolactinemia and osteopenia (a T-score between −2.5 and −1.0) was associated not only with the normalization of prolactin levels, but also with the simultaneous normalization of testosterone levels." (PMID 38338751, 2024). "Elevated prolactin levels, a condition known as hyperprolactinemia, have been implicated in infertility in some women." (PMID 38525328, 2024). "To summarize, alongside recommending screening for PRL levels in severe obesity patients, we stress the importance of long-term correction of hyperprolactinemia and its linked hypogonadism." (PMID 38510701, 2024). "This review provides a detailed discussion of the current knowledge on the role of PRL in the context of ovulation and ovulatory disorders, particularly with regard to hyperprolactinemia, which is one of the most common causes of infertility in women." (PMID 38396659, 2024). "The main detectors of ovulatory disorders are PRL and LH, which manifest as hyperprolactinemia and LH deficiency, and ovarian polycystic changes are the key and consistent features of polycystic ovaries." (PMID 38606298, 2024). "The standard procedure in the case of hyperprolactinaemia involves the use of dopamine D2 receptor agonists if elevated prolactin levels cause symptoms." (PMID 38429692, 2024). "Macroprolactinemia, which is defined as the quantitative predominance of an isoform of a greater molecular weight than PRL known as macroprolactin (big–big PRL), is a common cause of hyperprolactinemia." (PMID 38396659, 2024). "While PRL is essential for pregnancy, studies suggest that elevated levels of serum PRL (hyperprolactinemia) are associated with adverse pregnancy outcomes, including miscarriage, preterm birth, and preeclampsia." (PMID 39763651, 2024). "Levosulpiride is a dopamine D2 receptor antagonist that induces hyperprolactinemia by blocking dopamine receptors in the pituitary lactotrophs causing inhibition of PRL release." (PMID 37673971, 2024). "In the case of hyperprolactinemia, inquiring thoroughly about its associated side-effects is essential, and strategies to reduce prolactin levels should be considered (i.e. dose reduction, switching to an alternative antipsychotic or adding aripiprazole)." (PMID 38995314, 2024). "This, in turn, stimulates the secretion of prolactin and causes the development of hyperprolactinemia." (PMID 38075053, 2023). "Nevertheless, it should be noted that migraine-like headaches associated with hyperprolactinemia are often unresponsive to common preventive medication for migraine and only resolve after normalisation of PRL levels." (PMID 36967387, 2023). "Because prolactin lowers both estrogen and testosterone production, hyperprolactinemia is associated with infertility in men as well as in women." (PMID 37759839, 2023). "As macroprolactinomas are associated with longer lasting hyperprolactinemia and related hypogonadism, the significantly higher rates of baseline PRL levels in the EO cohort probably reflect on the longer disease duration in more oligosymptomatic men." (PMID 36814862, 2023).
hyperprolactinemia (continued). "These tumors cause excessive secretion of prolactin (hyperprolactinemia), a hormone responsible for lactation." (PMID 37905282, 2023). "Hyperprolactinemia has also been identified as a risk factor for stroke, and this association was attributed to the chronic prolactin excess-induced increase in platelet reactivity." (PMID 37242186, 2023). "Despite the fact that both serum prolactin levels and bone regulation involve complex mechanisms, hyperprolactinemia induced by antipsychotics has been implicated in bone loss." (PMID 37875841, 2023). "The investigators found that hyperprolactinemia induced by prolactin-raising antipsychotics was associated with low bone mass more in men than in women." (PMID 37759839, 2023). "Some consequences of long-term exposure to antipsychotic drugs that increase prolactin levels were recently described, such as a greater risk of breast cancer and low-energy fractures, indicating that hyperprolactinemia needs to be monitored in these patients." (PMID 37603404, 2023). "During IVF, variations in prolactin levels were reported, characterized as transient hyperprolactinemia, possible causes being gonadotropins and GnRH agonists administration, increased estradiol levels and procedure-related stress." (PMID 36678618, 2023). "Since there is no complete antagonism of dopamine receptors, there is still dopamine available to inhibit excessive prolactin release, lowering the risk of developing hyperprolactinemia." (PMID 38143631, 2023). "Several previous studies showed that PRL was associated with increased CRP in individuals with hyperprolactinemia and older adults, whereas it was weakly correlated with CRP in male patients." (PMID 35222274, 2022). "The insertion of an i.v. catheter 15–20 min before sampling for PRL assay in the diagnostic phase is a simple and practical tool in cases of mild hyperprolactinemia." (PMID 35000899, 2022). "Subsequently, infusion of PRL or administration of dopamine agonist causing hyperprolactinemia resulted in adenomyosis in the mouse." (PMID 35773139, 2022). "This review focuses on the role of PRL and hyperprolactinemia on important CVD risk factors such as systemic arterial hypertension, dyslipidemia, atherosclerosis, endothelial dysfunction, glucose metabolism, and body weight." (PMID 36704037, 2022). "Central nervous system (CNS) tumors that produce prolactin, called prolactinomas, also cause hyperprolactinemia." (PMID 36733805, 2022). "Because both risk factors (reduced fecundity and breastfeeding) associate with hyperprolactinemia, PRL was suggested as a biological explanation." (PMID 35721729, 2022). "Whenever an iatrogenic cause of hyperprolactinemia is suspected, PRL measurement should be repeated after discontinuing the culprit medication for 3–4 days." (PMID 35000899, 2022). "About 20% of women taking combined oral contraceptives develop mild hyperprolactinemia, but it should be kept in mind the possibility of a concomitant organic cause for PRL elevation in cases of moderate-severe hyperprolactinemia (>50 ng/mL)." (PMID 35000899, 2022). "Risperidone, paliperidone, and amisulpride were the top three antipsychotics associated with the risk of increased PRL concentration in the blood and hyperprolactinemia according to their RRR values." (PMID 36313772, 2022). "Another reason for observed findings can be an aromatization of exogenous testosterone to estradiol which stimulates pituitary gland to PRL production and cause secondary hyperprolactinemia." (PMID 36014950, 2022). "Recurrence of hyperprolactinemia was associated with both nadir serum prolactin and nadir tumor diameter immediately prior to cabergoline withdrawal, and tumor diameter at diagnosis." (PMID 36013562, 2022). "A large group of drugs, including psychotropic drugs like antipsychotics, have the potential to cause the hypersecretion of PRL, which is the most common pharmacological cause of hyperprolactinemia." (PMID 36313772, 2022).
hyperprolactinemia (continued). "Hyperprolactinemia causes a vast array of unfavorable metabolic effects but suppressed prolactin levels can also increase cardiometabolic risk." (PMID 36246929, 2022). "Macroprolactin is an isoform of PRL with a greater molecular weight but reduced biological activity, occurring in about 20% of cases and associated with asymptomatic hyperprolactinemia." (PMID 36237192, 2022). "She associated hyperprolactinemia (a prolactin value 3 times above the normal upper limit) and mild hypercholesterolemia." (PMID 36359512, 2022). "In healthy women, the high estrogen levels in pregnancy cause lactotroph hypertrophy and hyperprolactinemia, and serum PRL levels gradually elevate during the course of gestation; thus, serum PRL is not an indicator of prolactinoma progression." (PMID 35892862, 2022). "While there are many causes of elevated prolactin levels, prolactinomas are the leading cause of hyperprolactinemia." (PMID 36246929, 2022). "Prolactinomas are common pituitary neuroendocrine tumors (PitNET) derived from prolactin (PRL)-producing cells that cause hypogonadism and infertility due to hyperprolactinemia." (PMID 35892862, 2022). "By blocking D2 receptors, antipsychotics eliminate the inhibitory effect of dopamine on prolactin secretion and thus can all cause hyperprolactinaemia." (PMID 35958655, 2022). "Blockade of dopamine D2 receptors in the tuberoinfundibular dopamine pathway causes prolactin release and can lead to hyperprolactinemia if antagonists of dopamine D2 receptors are used." (PMID 36438799, 2022). "In pathological hyperprolactinemia, PRL predisposes to obesity, induces visceral fat depot hypertrophy, and decreases lipogenesis." (PMID 36704037, 2022). "Mass lesions of the hypothalamus or pituitary stalk cause the dopamine inhibition of PRL to be insufficient, resulting in hyperprolactinemia." (PMID 35892862, 2022). "For example, SSRIs induce hyperprolactinemia due to 5-HT-induced increase in prolactin (PRL) release causing sexual dysfunction, and this effect would be mitigated by increased DA." (PMID 36262632, 2022). "This distinction is important to keep in mind when differentiating prolactin secreting tumors from other causes of hyperprolactinemia." (PMID 36246929, 2022). "Initial high serum PRL levels have been associated with recurrence of hyperprolactinemia, corroborating our results." (PMID 35250868, 2022). "Due to the heterogeneous nature of PCOS, it is possible that both hyperprolactinemia and low prolactin are associated with different phenotypes of PCOS." (PMID 36457554, 2022). "Hyperprolactinemia causes HGH by inhibition of GnRH secretion in the hypothalamus caused by excess prolactin, which also causes a decline in FSH and LH hormone levels." (PMID 34359947, 2021). "Following identification of a potential drug-induced cause of hyperprolactinaemia, discontinuation of the suspected drug usually results in normalisation of serum prolactin levels and restoration of a normally functioning HPG axis." (PMID 34360982, 2021). "Acyclicity has been linked to chronically high levels of circulating prolactin (a pituitary disorder called hyperprolactinemia) with an increased probability of developing the longer the elephant is acyclic." (PMID 34930501, 2021). "The adenoma can cause acromegalic manifestations by producing excessive GH, hyperprolactinemia by secreting prolactin or compressing the pituitary stalk, and hypopituitarism in at least one axis by damaging the pituitary gland." (PMID 35154007, 2021). "Compared with the tumor itself, the serum prolactin level seems to be more sensitive to the DAs withdraw, and the risk of hyperprolactinemia recurrence was very high." (PMID 34774043, 2021). "The major cause of pathological hyperprolactinemia involves tumours of pituitary lactotroph cells (prolactinomas), the main source of PRL in the organism." (PMID 34158080, 2021).